INS (insulin)
Diseases named in the same sentence as INS in open-access papers (continued):
Sharing a sentence is not in itself a finding about the gene and the disease.
diabetes (continued). "The peroxisome proliferator-activated receptor (PPAR) is a nuclear receptor superfamily and has three isotypes α, δ, and γ that can regulate lipid metabolism, inflammation, and insulin sensitivity as well as insulin production and secretion for treating diabetes." (PMID 31652794, 2019). "This has formed a basis of many studies in 1990s like Diabetes Interventional Study, Kumamoto study, DIGAMI (Diabetes and Insulin-Glucose infusion in Acute Myocardial Infarction) study, and STOP-NIDDM (Study TO Prevent NIDDM) trial to control the postprandial hyperglycemia in order to prevent CVD." (PMID 31929794, 2019). "Adherence to insulin therapy is a critical factor for adequate control of diabetes mellitus." (PMID 31692777, 2019). "In order to make these resources more accessible to the scientific community, the Islet Gene View was created, providing comprehensive information on gene expression in relation to diabetes status, insulin secretion, expression of other pancreatic genes and related phenotypes of interest." (PMID 31161346, 2019). "These factors could also affect access to structured diabetes education which itself improved access to intensive insulin regimens." (PMID 31604437, 2019). "The disorder of insulin signal transduction plays an important role in the pathogenesis of diabetes, so it has important significance with the study of insulin signal transduction, and the metabolic function of insulin is mainly mediated by the PI3K/Akt pathway." (PMID 31212585, 2019). "Bifidobacterium is shown to be lower in abundance in patients with diabetes compared to healthy individuals, in insulin-resistant versus insulin-sensitive morbidly obese individuals, and in pregnant women with gestational diabetes compared to healthy pregnant women." (PMID 30987356, 2019). "It was seen that anxiety score of more than 10 was more common in female gender, older participants, individuals with longer duration of diabetes, those taking non-insulin treatment, individuals with painful neuropathy and nephropathy, and those admitted with HHS." (PMID 31131177, 2019). "A number of studies in both human and rodents have been conducted to investigate the effects of SGs on diabetes biomarkers such as blood pressure (BP), fasting blood glucose, and insulin etc., and it has been reported that SGs exhibit some antidiabetic capabilities." (PMID 31438580, 2019). "Two hundred and twenty six participants (50.2%) used insulin on its own for diabetes control." (PMID 30654784, 2019). "Thyroid function may alter carbohydrate metabolism via influence of insulin, which may in terms of derangement of thyroid function and insulin function result in the development of type 2 diabetes mellitus (T2D)." (PMID 31096476, 2019). "Previous studies in general practice and hospital settings have identified that prescribing of non-insulin diabetes medications may be sub-optimal in people with type 2 diabetes (T2D) and renal impairment." (PMID 30777033, 2019). "Duration of diabetes mellitus and perceptions about insulin use (n=300)." (PMID 30881393, 2019). "In fact, insulin has been shown to stimulate both the expression of mitochondrial fusion proteins as well as overall mitochondrial function in rat cardiomyocytes, further strengthening the link between insulin signaling, diabetes, and mitochondria." (PMID 31216686, 2019). "What is known is that there are four factors which all contribute to the development of diabetes (diabetes factor; DF), i.e., increased insulin resistance (IR), decreased insulin secretion both first- and second-phase (FPIS, SPIS, respectively), and decreased glucose effectiveness (GE)." (PMID 31482956, 2019). "In fact, these Authors state that “...Reduced insulin sensitivity alone does not cause diabetes...”." (PMID 31600232, 2019). "Interestingly, we found similar metabolic dysregulations in individuals with prediabetes and diabetes to those of insulin-resistant individuals with normal glucose metabolism." (PMID 31779625, 2019).
diabetes (continued). "In addition, the administration of GLP-1 in an obese mice model of diabetes reduced the oxidative stress and the inflammatory state in adipocytes and macrophages, contributing to the improvement in insulin sensitivity." (PMID 30970605, 2019). "However, most of the plant treated groups showed a reduced ratio of TG/HDL-C, indicating the potential improvement of insulin sensitivity in diabetes." (PMID 31640743, 2019). "In this study, both mIAA and IA2A were associated with an unmethylated INS ratio close to diabetes onset (within 0–2 months prior to diagnosis), but not at baseline (24 months prior to diabetes onset)." (PMID 31398795, 2019). "Diabetes is a serious disease, classified as chronic, that occurs either when the pancreas does not produce enough insulin (a hormone that regulates blood glucose), or when the body cannot effectively use the insulin well." (PMID 31242688, 2019). "Regarding the antidiabetic effect, FFA1 has been widely investigated as a molecular target for diabetes, mainly due to the glucose-stimulated insulin secretion via protein kinase C/inositol triphosphate (PKC/IP3) activation and, consequently, intracellular calcium increase, inducing insulin release." (PMID 31035457, 2019). "Studies into how this apparent re-sensitisation to amylin and insulin occurs could give insights on how to better treat and manage diabetes in human patients." (PMID 31601900, 2019). "Patients with uncontrolled diabetes might be treated by the complementary action of insulin plus DPP-4 inhibitors." (PMID 30611254, 2019). "In brief, clinical trials involving different countries and different people showed that tea could prevent and manage diabetes mellitus and its complications, mainly by improving insulin resistance and decreasing postprandial blood sugar." (PMID 31185622, 2019). "TIDM is an autoimmune disease that is characterized by slowly progressing pancreatic beta-cell destruction, resulting in a reduction of insulin secretion and, over the course of several years, the development of clinically evident insulin-dependent diabetes mellitus." (PMID 31574933, 2019). "Insulin replacement restores hypothalamic signaling at early stages of diabetes." (PMID 31620084, 2019). "TNF-α can block insulin signal transduction in skeletal muscle by JUN amino terminal kinase (JNK), eventually affect glycometabolism, which is associated with the incidence of diabetes." (PMID 31341840, 2019). "In addition, troxerutin had a better effect than insulin on diabetes-induced testicular structural damage." (PMID 30834086, 2019). "There is a high proportion of patients treated with insulin monotherapy, i.e., 20%, which is higher than that reported in previous studies and is not consistent with the ADA and European Association for the study of Diabetes (EASD) guidelines." (PMID 31297092, 2019). "Therefore, when selecting antihypertensive agents for hypertensive patients with type 2 diabetes mellitus, not only the antihypertensive effect but also effects on insulin sensitivity, glucose metabolism, and lipid metabolism should be considered." (PMID 30943275, 2019). "For example, we did not have information on the duration of diabetes, but we did attempt to reduce associated errors by excluding insulin-treated patients (likely to have longer duration of diabetes)." (PMID 30927105, 2019). "In diabetes, after the combination of insulin and growth factor receptor tyrosine kinases, PI3K is activated and generates phosphatidylinositol 3,4,5-trisphosphate, which induces the phosphorylation of AKT (p-AKT); p-AKT then activates endothelial nitric oxide synthase (eNOS) and produces NO." (PMID 31686985, 2019). "The higher early diastolic mitral inflow velocity (E) and E/E' ratio in diabetes patients treated with insulin, compared to the other patient groups, suggested insulin‐treated patients had higher left ventricular end‐diastolic pressure and more diastolic dysfunction than the other participants." (PMID 31271255, 2019).
diabetes (continued). "Additionally, lower UIC has been found among patients with diabetes and obesity compared to control subjects, and urinary iodine was shown to be negatively correlated with glucose, insulin levels, and HOMA-IR." (PMID 31379740, 2019). "Thus, DPP-IV inhibitors play a major role in type-2 diabetes mellitus in which insulin secretion and blood glucose level stability are of great importance." (PMID 31181665, 2019). "Hyperketonemia in diabetes is due to insufficient insulin action." (PMID 31861135, 2019). "Studies with adults have shown risk of type 2 diabetes mellitus (DM2) development to be highly associated with increased CRP, suggesting that low-grade chronic inflammation coexists with glucose intolerance and compensatory increase in insulin secretion." (PMID 31143476, 2019). "It remains to be fully elucidated whether the use of metformin, an insulin sensitizer, and/or sulfonylureas, insulin secretagogues, affects cancer incidence in subjects with type 2 diabetes mellitus." (PMID 31828167, 2019). "This demonstrates the importance of insulin-stimulated glucose uptake to fatty acid metabolism (and vice versa) and therefore cardiac efficiency and performance and exemplifies potential defects in these systems in diseases such as diabetes." (PMID 31920989, 2019). "Case 8 developed diabetes mellitus immediately after surgery and required insulin treatment." (PMID 31208162, 2019). "In particular, in order to understand quantitatively the interplay between insulin sensitivity, pancreatic β-cell responsiveness and β-cell population dynamics, several mathematical models of the long-term development of Type 2 Diabetes Mellitus (T2DM) have been formulated." (PMID 31600232, 2019). "In this study, we found that remission of type 2 diabetes after bariatric surgery was inversely associated with duration of diabetes and was highest among patients with recent onset and those without insulin treatment." (PMID 31747392, 2019). "The doses of lyophilized SSE used in this study, were similar to the dose recommended for drinking by traditional medicinal practitioners, giving an additional support for the traditional use of this plant for the treatment of diabetes, insulin resistance and related pathologies." (PMID 31847157, 2019). "As insulin becomes an increasingly common treatment for patients with type 2 diabetes, these findings highlight the critical need for studies of the comparative effects of continuing versus stopping insulin secretagogues and newer diabetes medications after insulin is started." (PMID 30759121, 2019). "However, in long-term treatment of diabetes, hyperglycemia is a relatively common reaction and one of the emergencies especially in the use of insulin, which acts as hypoglycemic factor." (PMID 30621321, 2019). "Nevertheless, it is still unknown that the over-degradation of ornithine to putrescine are due to diabetes itself or to insulin resistance." (PMID 30833930, 2019). "The mechanism of STZ-induced diabetes includes selective destruction of pancreatic β-cells, which may make cells less active and result in poor sensitivity of insulin for glucose uptake by tissues and hyperglycemia." (PMID 31443712, 2019). "Diabetes mellitus (DM) is a chronic progressive metabolic disorder characterized by hyperglycemia with disturbances of carbohydrate, fat, and protein metabolism, mainly due to defects in insulin secretion, insulin action, or both." (PMID 31049023, 2019). "Diabetes is a metabolic disorder caused by a lack of insulin and insulin dysfunction characterized by hyperglycemia." (PMID 31717970, 2019). "PKC was found to be elevated in diabetes and abrogated insulin signaling." (PMID 30800211, 2019). "In addition to restoring islet function and improving insulin resistance, these mechanisms are also conducive to prevent the development of diabetes-related complications." (PMID 30906411, 2019).
diabetes (continued). "In a model of streptozotocin-induced diabetes in rats, H2S formation was significantly increased in homogenates of the pancreas and liver of diabetic animals, as compared to healthy animals, and insulin treatment of streptozotocin-challenged rats reversed the increase in H2S-synthesizing activity." (PMID 31178664, 2019). "According to the Treatment Guideline for Diabetes in Korea, insulin injections are prescribed for type 1 diabetes, while oral hypoglycemic agents are prescribed first for type 2 diabetes, and if glycemic control is not good, use of both oral hypoglycemic agents and insulin injections is considered." (PMID 31726788, 2019). "In our search for the natural compounds of wild mushrooms that improve insulin secretion, we found Annulohypoxylon annulatum, and its isolated secondary metabolites, can be a possible candidate to treat diabetes; it has been reported to inhibit tumor angiogenesis." (PMID 31382473, 2019). "Evidence from systematic review and meta-analysis of randomized controlled trials suggests that statins can increase adiponectin concentrations despite its negative effect on insulin sensitivity and risk for developing diabetes mellitus." (PMID 31920962, 2019). "However, the relationship between blood UA and decreased insulin sensitivity in patients with type 1 diabetes mellitus is weaker than in healthy subjects." (PMID 31737070, 2019). "Use of insulin and glyburide increased in prevalence over the pregnancy period, which is likely due to a combination of newly diagnosed gestational diabetes and a switch to these treatments from other oral drugs among women with pre-existing diabetes." (PMID 31775682, 2019). "We found insulin signaling to be a major pathway as per the results observed in zebrafish, though other obesity- or diabetes-related pathways may also be affected following Cenpx knockdown." (PMID 31417608, 2019). "Besides, strengthening of information, education, and communication (IEC) on the issue of diabetes and insulin self-administration using mass media (television/radio) plays paramount importance." (PMID 31915711, 2019). "In the future, it could be interesting to introduce structured courses about the use of technology in diabetes, carbocounting, and insulin dose adjustment alongside the intervention we proposed in the current study." (PMID 31871949, 2019). "Current insight is that optimal biocompatible devices can be created which raises optimism that immunoisolating devices can be created that allows for long term survival of encapsulated replenishable insulin-producing cell sources for treatment of Type 1 Diabetes Mellitus." (PMID 31214587, 2019). "We also added two items “I have consistent routines for monitoring blood glucse levels and taking insulin” and “I know how to find a new diabetes care provider if one were needed” based on suggestions by interviewees that these were important topics to address." (PMID 31858284, 2019). "Of note, women using rtCGM more often used insulin pumps and had a longer duration of diabetes." (PMID 30904938, 2019). "Type 1 Diabetes Mellitus (T1DM) has long required insulin treatment." (PMID 31415414, 2019). "Type 2 diabetes mellitus (DM) is characterized by hyperglycemia and abnormal carbohydrate, lipid, and protein metabolism; it is a multifactorial condition triggered by disturbances of insulin activity in peripheral tissues." (PMID 30791362, 2019). "Circumstantial evidence of an altered β cell phenotype in clinical diabetes was revealed by the observation of co-localization of insulin with glucagon or vimentin (a mesenchymal marker) in a distinct subset of cells in human pancreas sections from subjects with T2D." (PMID 31401713, 2019). "Type 1 diabetes mellitus (T1D) is a chronic disease characterized by autoimmune destruction of beta cells in the pancreas, which is responsible for the synthesis and exertion of the insulin." (PMID 31341469, 2019).
diabetes (continued). "Organized researches indicate that Cdc42 is a crucial member during the progression of diabetes, and Cdc42 not only participates in the process of insulin synthesis but also regulates the insulin granule mobilization and cell membrane exocytosis via activating a series of downstream factors." (PMID 30621321, 2019). "We also found that HFpEF patients with insulin‐treated diabetes had worse health‐related quality of life and were twice as likely to experience CV death or HF hospitalization, even after extensive adjustment for other prognostic variables including NT‐proBNP and eGFR." (PMID 31271255, 2019). "Patients in the T2DKD, T2DNRF and CCKD groups were prescribed medications such as angiotensin converting enzyme (ACE) inhibitors or angiotensin II receptor blockers (ARBs), statins, oral hypoglycaemic drugs and/or insulin to manage hypertension, dyslipidaemia and diabetes respectively." (PMID 31358876, 2019). "Therefore, the effect of intraperitoneal administration of a single dose of liposomal curcumin can achieve the target for prevention or management of diabetes by the insulin-secreting beta cells function preservation." (PMID 30818888, 2019). "Several multistep protocols have been described to differentiate human embryonic or inducible pluripotent stem cells into pancreatic progenitors able to undergo in vivo maturation with generation of glucose sensitive insulin secreting cells able to reverse diabetes in mice." (PMID 30191384, 2019). "Closed‐loop systems, which automatically and continuously adjust insulin delivery according to real‐time sensor glucose levels, may reduce burden of diabetes management." (PMID 31140654, 2019). "Moreover, by adopting propensity score modeling (MatchIt), we assessed the effects of insulin delivery method on health outcomes in patients with diabetes treated with insulin." (PMID 31461470, 2019). "Moreover, we found no clinically remarkable changes from the baseline values concerning other diabetes-related variables, such as fasting blood glucose, fasting insulin, HbA1c (NGSP), HOMA-β, or 1, 5-AG, in either group." (PMID 30943275, 2019). "Chronic hyperglycaemia further impairs insulin secretion, enhancing hyperglycaemia and triggering a vicious cycle that fuels a progressive deterioration in β-cell function and conversion of impaired glucose tolerance to frank diabetes." (PMID 31171772, 2019). "The present study showed that troxerutin administration, similar to insulin, could relatively improve the diabetes-induced decrease in quantity and quality parameters of sperms." (PMID 30834086, 2019). "The results were further supported by the presence of fewer insulin immunopositive sites in diabetic pancreas, however the treatment of 50 or 100 mg/kg A. reticulata seed extract or metformin significantly improved the insulin immunopositive sites in diabetic rats." (PMID 31708869, 2019). "These may be cardiovascular in nature (such as stroke) or due to other causes such as hypoglycemia; here it is notable that 37% of patients with diabetes in SCD-HeFT were treated with insulin at baseline." (PMID 30689020, 2019). "We investigated the effect of macronutrient content in a meal on postprandial glycemia and we identified factors that may make it difficult to determine the appropriate dose of insulin to compensate for food intake in people with diabetes." (PMID 30871141, 2019). "Indeed, stem cell therapy can improve diabetes treatment through differentiation of stem cells into insulin- producing cells, regeneration of pancreas, amending of insulin resistance, and modulation of immune system." (PMID 32351908, 2019). "This fact is of tremendous importance since in addition to necessary insulin therapy and customized diet, physical activity is an indispensable element of diabetes control that favorably affects a patient’s condition and contributes to the positive effects of therapy." (PMID 31546871, 2019).